LCN2 (lipocalin 2)
Diseases named in the same sentence as LCN2 in open-access papers (continued):
Sharing a sentence is not in itself a finding about the gene and the disease.
Glucose intolerance (11 papers, 2010 to 2025). Glucose intolerance (GI) can be defined as dysglycemia that comprises both prediabetes and diabetes. "Reduction of PPAR-γ expression and generation of a pro-inflammatory environment by increased lipocalin-2 expression in white adipose tissue may contribute to stress-induced glucose intolerance." (PMID 27538526, 2016). "Interestingly, while the expression of Lcn2 and the levels of corticosterone normalized after recovery, the glucose intolerance phenotype and the lower expression of PPAR-γ prevailed after 5 weeks of recovery from stress." (PMID 27538526, 2016). "In summary, our experimental work shows that the metabolic effects of chronic stress persist after a period of recovery and that the glucose intolerance triggered by chronic stress is associated with a decrease in the expression of PPAR-γ and a transient overexpression of Lcn2 in the vWAT." (PMID 27538526, 2016). "Despite these results it is still a matter of debate whether this Lcn2 overexpression is beneficial or detrimental to the glucose intolerance phenotype." (PMID 27538526, 2016).
osteoporosis (11 papers, 2020 to 2025). A condition of reduced bone mass, with decreased cortical thickness and a decrease in the number and size of the trabeculae of cancellous bone (but normal chemical composition), resulting in increased fracture incidence. "Lipocalin-2 is linked to poor bone microarchitecture in mice and is even suggested to mediate osteoporosis development from prolonged disuse." (PMID 38516409, 2024). "We aimed to investigate if plasma lipocalin-2 could be utilized as a biomarker for WNT1 and PLS3 osteoporosis and to evaluate the association between lipocalin-2 and other parameters of bone metabolism." (PMID 36157448, 2022). "Given the reported increase in circulating LCN2 levels with aging, future studies are warranted to explore its potential contribution to age-related iron dysregulation and osteoporosis." (PMID 40343339, 2025). "Adefovir causes increased bone loss in patients by binding to LCN2, while CXCL8, a specific target of tenofovir, interferes with the expression of CXLC8, and patients ultimately experience adverse events of osteoporosis." (PMID 40687725, 2025). "To provide more evidence, we detected LCN2 protein and RNA expression in clinical specimens and found that the expression of LCN2 was increased in osteoporosis patients, which was mutually supportive of the RNA-seq results." (PMID 37749079, 2023). "Future studies should explore whether interventions to reduce LCN2 can prevent age-related diseases, such as cardio-metabolic disease, osteoporosis, and sarcopenia, and whether LCN2 can be used as a biomarker for chronic disease." (PMID 39830147, 2025). "In addition, LCN2 levels are increased in response to unloading suggesting that it may mediate the development of osteoporosis from disuse." (PMID 36831180, 2023). "Recognizing that LCN2 and other hepatic innate immune serum factors are elevated in individuals afflicted by inflammatory bowel conditions, and that these individuals have an increased prevalence of osteopenia/osteoporosis, further underscores the relationship between the gut, liver, and bone." (PMID 32161843, 2020). "Importantly, we found that antibody-based blockade of Lcn2 reversed osteoporosis and marrow adiposity in Piezo1-deficient mice, suggesting that pharmacological/genetic inhibition of BMMSC-secreted Lcn2 may represent a promising pharmacotherapy for mechanical unloading-induced bone diseases." (PMID 41145414, 2025). "Given the reported link to DKK1 and its significance in bone metabolism, we sought to evaluate the significance and utility of lipocalin-2 as a novel biomarker in WNT1 and PLS3 osteoporosis and its correlations with other parameters of bone turnover as well as with parameters of iron metabolism." (PMID 36157448, 2022). "The current study investigated whether lipocalin-2 could be a novel biomarker for WNT1 and PLS3 osteoporosis and explored its relationship to other parameters of bone and mineral metabolism." (PMID 36157448, 2022). "Fortunately in the past few years, novel adipokines have been identified such as visfatin, LCN2, nesfatin-1, RBP-4, apelin, and vaspin that may have osteoprotective/osteoanabolic effects and thus could serve as potential therapeutic targets for osteoporosis and other metabolic bone diseases." (PMID 36831180, 2023). "Interestingly, ELISA performed in the mouse sera at the end of the experiment (10 weeks after the induction of osteoporosis) did not detect differences in soluble P-selectin and Lipocalin 2 in the osteoporosis groups versus their controls." (PMID 36282293, 2023). "However, the role of lipocalin-2 in WNT1 and PLS3 osteoporosis is unknown." (PMID 36157448, 2022). "Our group demonstrated both in vitro and in vivo that Lipocalin 2 plays a pivotal role in mechanical unloading-related processes, while it appears to have no implication in OVX-induced osteoporosis." (PMID 36282293, 2023).
osteoporosis (continued). "In conclusion, our study demonstrates that the circulating levels of lipocalin-2 are not altered in WNT1 and PLS3 osteoporosis, and therefore cannot be used as a metabolic biomarker in the diagnosis or for monitoring these two monogenic conditions." (PMID 36157448, 2022). "Our results suggest that lipocalin-2 is not a specific biomarker for WNT1 and PLS3 osteoporosis, but the correlation between lipocalin-2 and FGF23 indicates an association between these markers in bone biology." (PMID 36157448, 2022).
periodontitis (11 papers, 2014 to 2026). An acute or chronic inflammatory process that affects the tissues that surround and support the teeth. "It is unknown if LCN-2 expression is associated with both periodontitis and systemic diseases." (PMID 39516276, 2025). "LCN-2 was found to be overproduced in all cases of gingivitis and almost all cases of periodontitis, suggesting its potential as a marker for periodontal diseases." (PMID 39516276, 2025). "After treatment, its level in all the periodontitis groups decreased significantly compared to baseline; the lowest level of lipocalin-2 was detected in group I, followed by groups II and III." (PMID 36714082, 2022). "Further, reducing Lcn2 levels in wildtype mice alleviated periodontitis-related bone loss, but not in KO mice." (PMID 41927522, 2026). "Therefore, further research on the role of LCN-2 in both systemic diseases and periodontitis will be crucial for understanding the connection between these pathologies and uncovering new etiological factors in periodontitis." (PMID 39516276, 2025). "Therefore, the present study investigated the effects of adjunctive PCL nanofibers on clinical status and GCF lipocalin-2 levels in periodontitis patients." (PMID 36714082, 2022). "Eight weeks after starting therapy, the levels of GCF lipocalin-2 decreased significantly in LDD-treated periodontitis groups (I, II, and III), becoming non-significantly different from the clinically healthy group (VI)." (PMID 36714082, 2022). "Combined incorporation of OTC and ZnO into PCL nanofibers could be a potential curative tool in chronic periodontitis as an adjunct to SRP as it improved the clinical parameters and reduced the GCF lipocalin-2 levels." (PMID 36714082, 2022). "Baseline GCF lipocalin-2 levels in the current study were not significantly different between all the periodontitis groups (I, II, III, IV, and V)." (PMID 36714082, 2022).
preeclampsia (11 papers, 2015 to 2023). Preeclampsia is a hypertensive disorder of pregnancy that is characterized by new-onset hypertension with proteinuria presenting after 20 weeks of gestation, and depending on mild or severe forms may initially present with severe headache, visual disturbances, and hyperreflexia. "Increased concentrations of lipocalin 2 were described in metabolic diseases such as T2DM, preeclampsia, and PCOS." (PMID 34212049, 2021). "In preeclampsia, the peripheral subpopulation of “non-classical” CD16+ monocytes, which express CX3CR1, is increased in comparison to uncomplicated pregnancies, and they show up-regulation of some immunomodulating factors like clusterin, lipocalin-2 and leptin receptors." (PMID 33496844, 2021).
triple-negative breast carcinoma (11 papers, 2019 to 2025). An invasive breast carcinoma which is negative for expression of estrogen receptor (ER), progesterone receptor (PR), and human epidermal growth factor receptor 2 (HER2). "Humanized models or advanced in vitro systems are needed to fully capture LCN2’s metastatic role in triple-negative breast cancer (TNBC)." (PMID 41303420, 2025). "Lipocalin-2 (LCN2) is a 25 kDa glycoprotein that has been shown to be a multifunctional player in the metastasis of triple-negative breast cancer (TNBC)." (PMID 41303420, 2025). "In this study, we engineered a PEGylated liposomal system encapsulating lipocalin 2 (Lcn2) small interfering RNA (Lcn2 siRNA) for selective targeting MBC cell line MCF-7 and triple-negative breast cancer cell line MDA-MB-231." (PMID 33916786, 2021). "In triple-negative breast cancer mouse model, local and systemic levels of MMP-9, VEGF, chitinase-3-like protein 1 (CHI3L1) and Lipocalin-2 (LCN2) induced by TAMs mediate cancer metastasis." (PMID 31629410, 2019).
acute coronary syndrome (10 papers, 2011 to 2025). Signs and symptoms related to acute ischemia of the myocardium secondary to coronary artery disease. "A recently published meta-analysis has shown that elevated LCN2 was linked to major adverse cardiovascular events in acute coronary syndrome patients." (PMID 39403549, 2024). "Previous studies have shown that patients with acute coronary syndrome also have increased levels of serum CRP, which are positively associated with serum LCN2 levels even after adjusting for several confounders." (PMID 24359145, 2013).
aneurysm (10 papers, 2015 to 2023). Bulging or ballooning in an area of an artery secondary to arterial wall weakening. "In patients with abdominal aortic aneurysm (AAA), hepcidin is markedly induced in smooth muscle cells (SMCs) of the aneurysm wall and inversely correlated with the expression of LCN2 (lipocalin-2), a protein implicated in AAA pathology." (PMID 36951059, 2023). "When we examined the source of LCN2 in the aneurysm wall, we observed it colocalized with the peripheral neutrophil marker Ly6g+Ly6c." (PMID 36951059, 2023). "Together, these findings give rise to a model in which, HAMP-mediated suppression of local LCN2 expression dampens neutrophil infiltration into the aneurysm wall, and promotes reparative autophagy in SMCs (graphic abstract)." (PMID 36951059, 2023).
bacteremia (10 papers, 2011 to 2025). "The gene encoding for lipocalin-2 (Lcn2), a siderophore sequestering protein, was the most highly upregulated during A. baumannii bacteremia, of the targets assessed, and corresponds to robust LCN2 expression in tissues." (PMID 36054235, 2022). "Although disruption of Lcn2 expression did not impact the number of bacteria recovered from tissues of mice infected using a model of bacteremia, Lcn2-/- mice were more susceptible to mortality from this infection." (PMID 36054235, 2022). "The LCN2 concentration was significantly higher in patients with bacteremia, as well as with lytA-PCR positivity and bacterial load in blood." (PMID 37317134, 2023). "Given the strong upregulation of Lcn2 in the A. baumannii infected host during bacteremia, we sought to determine if this translates to increased production of the LCN2 protein in vivo." (PMID 36054235, 2022). "We demonstrate that nutritional immunity is robustly induced during A. baumannii bacteremia, and that LCN2 is an essential part of this response." (PMID 36054235, 2022). "A probable explanation for not observing differences in burdens between WT and Lcn2-deficient mice in the bacteremia model is that the bacterial density simply cannot get higher than in the WT mice, for reasons including constraints on space or in resources." (PMID 36054235, 2022). "Unlike in the murine model of bacteremia, the bacterial burdens recovered from Lcn2-deficient mice relative to their WT counterparts were significantly higher in every organ assessed, as well as the blood, by ~1.5 to 2.8-log10." (PMID 36054235, 2022). "LCN2 was not required to control bacterial growth during bacteremia but was protective against mortality." (PMID 36054235, 2022). "Previous findings are mirrored by our own observations of A. baumannii bacteremia in mice, although this study appears to represent the first to use an intravenous model of infection to interrogate the role of LCN2 in Gram-negative bacteremia." (PMID 36054235, 2022). "Using multiple murine models of infection in Lcn2+/+ and Lcn2-/- backgrounds, we show that GltA is a fitness factor during lung infection by direct and hematogenous routes but is not necessary for bacteremia." (PMID 31449551, 2019). "The impact of LCN2 on the pathophysiology of A. baumannii bacteremia appears to function independent of restricting bacterial growth through iron and/or siderophore sequestration under the conditions tested and may be multifactorial." (PMID 36054235, 2022).
cervical carcinoma (10 papers, 2014 to 2026). A carcinoma arising from either the exocervical squamous epithelium or the endocervical glandular epithelium. "In the cervical cancer patients examined, elevated expression of LCN2 was significantly associated with lymph node involvement in patients with SCC." (PMID 26840566, 2016). "The aim of our study was to determine whether serum LCN2 could serve as a diagnostic marker of cervical cancer (CC) and to evaluate the correlation between its serum concentration, the clinical stage of the cancer and Human Papilloma Virus HPV infections in women." (PMID 31151292, 2019). "Notably, the mechanisms underlying LCN2 actions in cervical cancer are still unclear." (PMID 26840566, 2016). "Conversely, AKR1C3 silencing upregulated LCN2 expression, resulting in decreased cell migration, invasion, and cytoskeleton changes in cervical cancer cells." (PMID 38523637, 2024). "In vitro and in vivo studies in a xenograft model confirmed tumor-promoting role and provided evidence that LCN2 mediates cervical cancer through the EMT signaling pathway." (PMID 38645429, 2024). "By analyzing 90 clinical specimens, it was found that elevated LCN2 tissue expression in cervical cancer is correlated with tumor metastasis and cancer progression." (PMID 38645429, 2024). "In cervical cancer cells, treatment with LCN2‐neutralizing antibody reduced the migration and invasion of cells that overexpressed LCN2." (PMID 34342930, 2021). "In conclusion, LCN2 enhances migration and invasion abilities in cervical cancer cell lines, both in vitro and in vivo." (PMID 26840566, 2016). "Collectively, these results support a potential role of LCN2 in cervical cancer metastasis by promoting cancer cell migration and invasion through modulation of the EMT pathway components, Snail, Twist, N-cadherin, and fibronectin." (PMID 26840566, 2016). "Our oligonucleotide microarrays revealed that the oncogenic protein, lipocalin 2 (LCN2), is overexpressed in clinical specimens of cervical cancer." (PMID 26840566, 2016). "In accord with clinical observations demonstrating ectopic expression of lipocalin 2 (LCN2), an oncogenic protein associated with EMT, in malignant tumors, was significantly upregulated in cervical cancer and correlated with lymph node metastasis." (PMID 26840566, 2016). "In a study by Wang and colleagues, knockdown of nm23-H1 in SiHa uterine cervical cancer cells was shown to increase LCN2 promoter activity and gene expression, thereby decreasing cell migration and invasion." (PMID 26840566, 2016). "Here, we investigated the role of LCN2 in cervical cancer, focusing on the mechanism responsible for metastasis." (PMID 26840566, 2016). "In fact, LCN2 expression is higher in cervical carcinoma compared to high- and low-grade dysplasia tissue." (PMID 26840566, 2016). "To verify the overexpression of LCN2 in cervical cancer, we performed immunohistochemistry (IHC) on 90 clinical specimens, including those from SCC (n = 43), AD (n = 28), and adenosquamous cell carcinoma (ADSCC) (n = 19) patients." (PMID 26840566, 2016). "The positive correlation between AKR1C3 and negative LCN2 expression was linked to higher recurrence and poorer survival in cervical cancer patients." (PMID 38523637, 2024). "LCN2 expression was identified in three cervical cancer cell lines." (PMID 26840566, 2016). "LCN2 may stimulate cervical cancer cell metastasis by promoting cancer cell motility through activation of EMT pathway components." (PMID 26840566, 2016). "The EMT signaling-related gene, LCN2, was up-regulated ∼21-fold in clinical specimens of cervical cancer, supporting our hypothesis that LCN2 modulates cervical cancer progression through the EMT pathway." (PMID 26840566, 2016).
cervical carcinoma (continued). "Our findings collectively support a potential role of LCN2 in cancer cell invasion through the EMT pathway and suggest that LCN2 could be effectively utilized as a lymph node metastasis marker in cervical cancer." (PMID 26840566, 2016). "Thus, LCN2 appears to promote cell migration and invasion in C33A cervical cancer cells, both in vitro and in vivo." (PMID 26840566, 2016). "In addition, serum levels of LCN2 were also increased significantly patient with cervical cancer, suggesting it as a potential non-invasive biomarker for the diagnosis and prognosis of cervical cancer." (PMID 38645429, 2024). "To further confirm the involvement of the EMT pathway in LCN2-induced phenotypes, we used immunofluorescence staining to identify the expression and location of EMT-related proteins in cervical cancer cells." (PMID 26840566, 2016). "Thus, serum LCN2 may be useful as a circulating biomarker for cervical cancer distant metastases." (PMID 26840566, 2016). "LCN2 staining was most strongly detected in two pairs of SCC and AD, where it was found in the cytosol of cervical cancer cells." (PMID 26840566, 2016).
intracerebral hemorrhage (10 papers, 2019 to 2025). A cerebrovascular disorder characterized by bleeding into one or both cerebral hemispheres including the basal ganglia and the cerebral cortex. "LCN2 secreted from RA contributes to neuronal death in response to brain injury caused by intracerebral hemorrhage or exposure to antipsychotic drugs." (PMID 35440572, 2022). "In a mouse intracerebral hemorrhage model, increased LCN2 inhibited the function of system Xc−, thereby promoting ferroptosis." (PMID 40375133, 2025).